NLRP3 (NLR family pyrin domain containing 3)
Diseases named in the same sentence as NLRP3 in open-access papers (continued):
Sharing a sentence is not in itself a finding about the gene and the disease.
autoimmune disease (continued). "Prior studies have noted the importance of NLRP3 inflammasomes as regulators of many inflammatory diseases such as liver injury, autoimmune disease, and neurodegenerative disease." (PMID 33839695, 2021). "Current studies have proposed the role of NLRP3 inflammasome in autoimmune diseases and its clinical therapeutic potential." (PMID 34707607, 2021). "In summary, NLRP3 inflammasome participates in the initiation of autoimmune diseases, which serves as a checkpoint in innate immunity and adaptive immune dysfunction." (PMID 34707607, 2021). "All these contrasts and connect in various mechanism indicate the complexity of NLRP3 inflammasome in the pathogenesis of autoimmune diseases." (PMID 34707607, 2021). "In other autoimmune diseases, NLRP3 inflammasome can also induce differentiation and polarization of Th2, Th17, and dendritic cells." (PMID 34707607, 2021). "Among various inflammasome complexes, the NLRP3 inflammasome is characterized by its role in inducing various human autoinflammatory and autoimmune diseases." (PMID 33576136, 2021). "Nucleotide-binding oligomerization domain (NOD)-like receptor containing pyrin domain 3 (NLRP3) is the most fully characterized inflammasome which is involved in the amount of human inflammatory and autoimmune diseases." (PMID 34880753, 2021). "On the other hand, besides effect of NLRP3 inflammasome pathway, NLRP3 inflammasome can promote autoimmune diseases in some other manners." (PMID 34707607, 2021). "Served as a checkpoint in innate and adaptive immunity, aberrant activation and regulation of NLRP3 inflammasome plays an important role in the pathogenesis of autoimmune diseases." (PMID 34707607, 2021). "NLRP3 plays a vital role in autoimmune diseases, and NLRP3-induced maturation of pro-inflammatory cytokines is implicated in PD pathogenesis." (PMID 32296327, 2020). "NLRP3 inhibition is intensively investigated, as therapeutic target for infectious diseases, autoimmune diseases and autoinflammatory diseases." (PMID 30721409, 2019). "To date, NLRP3 inflammasome research has focused on the pathogenesis of a number of complex conditions, notably autoinflammation and autoimmune disease, that can be treated with the NLRP3-inhibitor MCC950 or the caspase-1 inhibitor Ac-YVAD-CMK." (PMID 30276509, 2019). "Among NLRPs, NLRP3 inflammasomes have been reported to participate in several chronic inflammatory and autoimmune diseases." (PMID 31182681, 2019). "Activation and regulation of NLRP3 inflammasome have been increasingly appreciated, it is intriguing for researchers to explore the roles played by NLRP3 inflammasome in IBD which is a common autoimmune disease in the GUT." (PMID 30873162, 2019). "The NLRP3 inflammasome plays a role in the pathogenesis of numerous inflammatory and autoimmune diseases such as diabetes, obesity, and atherosclerosis." (PMID 30140708, 2018). "The Leu-rich epitopes have also been shown to induce an IL-17 response in different autoimmune diseases such as NLRP3 (autoimmune encephalomyelitis), FLRT2 (systemic lupus erythematosus), and LGI1 (limbic encephalitis)." (PMID 29163505, 2017). "The NLRP3 inflammasome controls the response of the host to pathogens; precise regulation is required to limit autoimmune diseases." (PMID 27929086, 2016). "Investigating the role of NLRP3 inflammasome in autoimmune diseases." (PMID 40671401, 2025). "Given that NLRP3 inflammasome activation is correlated with the pathogenesis of various diseases, including neurological disorders, autoimmune diseases, and metabolic diseases, blocking the NLRP3 inflammasome activation pathway is widely considered an effective treatment for inflammatory diseases." (PMID 39985286, 2025).
autoimmune disease (continued). "Simultaneously, the study confirmed that the inhibitor of NLRP3 infalmmasome holds potential as a treatment for related autoinflammatory and autoimmune diseases, thus paving a new path for further exploring the significance of NLRP3 infalmmasome in human health and disease." (PMID 39717099, 2024). "Therefore, we identified NLRP3 inflammasome as a potential new therapeutic target in this severe complication of pro-female autoimmune disease for which specific inhibitors of NLRP3 are currently developed." (PMID 39654901, 2024). "NLRP3 inflammasome activation and ubiquitination are two major host innate immune events, involving multiple aspects, such as bacterial infection, autoinflammatory and autoimmune diseases." (PMID 38789414, 2024). "Inhibition NLRP3 inflammasome using the specific inhibitor MCC950 has achieved satisfactory therapeutic results not only in ALI model but also other inflammatory conditions including autoimmune diseases." (PMID 38218935, 2024). "Targeting the inhibition of the NLRP3 inflammasome could be a useful therapeutic strategy for autoimmune diseases, as this enzyme’s overactivation is a key factor in autoimmune responses." (PMID 38666950, 2024). "Notably, recent investigations highlight the significant involvement of NLRP3 inflammasomes in various autoimmune diseases, prompting an in‐depth exploration of their impact on MS." (PMID 39690733, 2024). "Our hypothesis is further supported by previous studies reporting that accumulated NETs can exacerbate autoimmune diseases and that NLRP3 can enhance NET formation in septic neuroinflammation." (PMID 38308301, 2024). "Because sustained activation of NLRP3 inflammasome results in progression to chronic inflammatory diseases, autoimmune diseases, cardiometabolic diseases, cancer, neurological disorders, and others, NLRP3 inflammasome inhibition in acute phases became a therapeutic target." (PMID 39199260, 2024). "However, the biological role of the NLRP3 gene in the immunopathogenesis of autoimmune diseases has been little documented." (PMID 36673016, 2023). "The critical roles of the NLRP3 gene in the immunopathogenesis of autoimmune diseases are still unknown." (PMID 36673016, 2023). "Additionally, we focus on the newly discovered bioactive substances for regulating the NLRP3 inflammasome in autoimmune diseases in the past three years." (PMID 37960237, 2023). "Dysfunctional NLRP3 inflammasomes are involved in the development of various autoimmune diseases." (PMID 37960237, 2023). "Uncontrolled activation of the NLRP3 inflammasome by non-pathogenic host stimuli has been implicated in the development of autoimmune disease." (PMID 38026692, 2023). "Therefore, some authors have proposed that NLRP3 plays a crucial role in the maintenance of tolerance conferring protection from autoimmune diseases." (PMID 35528000, 2022). "Therefore, it is reasonable to list P2X7R as a separate chapter to emphasize not only its profound effect in NLRP3 inflammasome activation, but also its potential as a shortcut pathway in the occurrence of autoimmune diseases." (PMID 35693810, 2022). "NLRP3 inflammasome promotes Th1 differentiation in RA, induced by IL-1β in a caspase-1-dependent manner, and it can also induce differentiation and polarization of Th2, Th17 and dendritic cells in other autoimmune diseases." (PMID 35457026, 2022). "Furthermore, the NLRP3 inflammasome is also responsible for autoimmune diseases due to an adaptive immune dysfunction." (PMID 35457026, 2022). "The inflammasome NLRP3 is a multiprotein complex that regulates caspase-1 activation and assists in releasing proinflammatory cytokine IL1β, one of the most characterized cytokines known to play an important role in autoimmune diseases." (PMID 35035661, 2022). "Studies of the roles of NLRP3 inflammasome in autoimmune diseases." (PMID 34707607, 2021).
autoimmune disease (continued). "Finally, the authors draw compelling connections between NLRP3, NETosis, and the notion that NETs serve as vectors for promotion of acute and chronic autoimmune disorders." (PMID 34639062, 2021). "However, there is evidence suggesting NLRP3 SNP as a dispose factor for several autoimmune diseases." (PMID 34790822, 2021). "Logically, NLRP3 inflammasome is involved in autoimmune diseases with adaptive immune dysfunction." (PMID 34707607, 2021). "More importantly, accurate understanding of the regulatory mechanisms is crucial to identify triggers of autoimmune diseases involved in NLRP3 inflammasome, and treatments targeted on it may show great therapeutic potential." (PMID 34707607, 2021). "The inhibition of NLRP3 inflammasome pathway, such as Ginsenoside Rg1, low methoxyl pectin, and Bay11-7082, may be a potential therapeutic strategy for autoimmune diseases." (PMID 34707607, 2021). "Therefore, delineating a comprehensive molecular mechanism of the complex role of NLRP3 inflammasome in autoimmune diseases deserves further study." (PMID 34707607, 2021). "Regulation of NLRP3 inflammasome activation and relevant pathway in autoimmune diseases." (PMID 34707607, 2021). "Finally, we discussed the effect of new-onset inhibitors of NLRP3 inflammasome in autoimmune diseases, which implies their potential therapeutic value for clinical applications deserved further study." (PMID 34707607, 2021). "While more insight into the specific mechanism of action is needed, this study provides an excellent example of not only the connections between NLRP3, NETosis, and chronic inflammation in autoimmune disease—but also potential stratagems to counter these interrelated molecular pathologies." (PMID 34639062, 2021). "Both TWIK2 and THIK1 channels could be attractive therapeutic targets for the treatment of NLRP3 inflammasome related autoimmune diseases in the future." (PMID 33424864, 2020). "Recent studies have shown that pyroptosis is a characteristic of autoinflammatory and autoimmune diseases; We found pyroptotic phenomena reflected as high expression of NLRP3, caspase-1, GSDMD, and IL-1β in endometrial cancer lesions as identified by IHC analyses." (PMID 31924176, 2020). "So NLRP3 is recognized as an important mediator of aseptic inflammation and autoimmune diseases." (PMID 32118052, 2019). "Interestingly some low penetrance NLRP3 CAPS mutations have been described in patients diagnosed with MS, suggesting a role for the inflammasome in the onset of autoimmune diseases." (PMID 31170158, 2019). "However, altered regulation of the NLRP3 inflammasome is found in several pathological conditions, including autoimmune disease and cancer." (PMID 31118894, 2019). "The NACHT domain of NLRP3 is closely related to the inherited autoimmune diseases such as CAPS." (PMID 30349539, 2018). "The NLRP3 inflammasome plays important roles in the pathogenesis of autoimmune diseases." (PMID 30140708, 2018). "Furthermore, we had previously shown that IL-1β, induced via caspase-1 and Nlrp3, plays a critical role in IL-17-mediated pathology in autoimmune disease." (PMID 23592988, 2013). "Moreover, finding the precise mechanism of how to maintain regulated NLRP3 activation might be the key to control various autoimmune diseases including pulmonary hypertension, which has yet to be investigated." (PMID 40948742, 2025). "The NLRP3 inflammasome signaling may play a critical role in both innate and adaptive immunity and act as a checkpoint in innate immunity to lead to skewed adaptive immune responses in autoimmune diseases." (PMID 38203796, 2024). "Therefore, small-molecule inhibitors of palmitoyl-acyltransferase ZDHHC7 or directly targeting NLRP3 Cys126 residue can potentially suppress inflammasome activation and thus may be useful for treating inflammation and autoimmune diseases." (PMID 38583156, 2024).
autoimmune disease (continued). "The pathological role of NLRP3 is not clear; however, genetic polymorphisms of NLRP3 are reported to have associations with autoimmune diseases such as Muckle–Wells syndrome, chronic infantile neurological cutaneous and articular syndrome, and familial cold auto-inflammatory syndrome." (PMID 36673016, 2023). "Therefore, how can the NLRP3 inflammasome function affect the development of autoimmune diseases?" (PMID 35457026, 2022). "Besides, compared to autoimmune diseases, renal involvement was much less common in NLRP3-AID." (PMID 35668534, 2022). "Thus, targeting NLRP3 is a promising strategy to treat autoimmune diseases." (PMID 35619184, 2022). "Studies focused on other NLRP3-associated clinical problems, such as post-myocardial infarction fibrosis and autoimmune diseases, have discovered that inhibition of NLRP3 inflammasome in the early phases of diseases may reduce the occurrence of severe, late-stage lesions." (PMID 36353625, 2022). "However, given that NLRP3, AIM2, and P2X7-NLRP3 are the most thoroughly studied in terms of pyroptosis in the context of autoimmune disease, we mainly introduce the biological characteristics of these inflammasomes and discuss their activation and modification patterns." (PMID 35693810, 2022). "In addition to NLRP3, mutation of NLRP1 also correlated with the occurrence of autoimmune disease." (PMID 35774778, 2022). "Collectively, the effect of NLRP3 inflammasome in autoimmune diseases involves the following two aspects: due to caspase-1 being the effector of inflammasome structure, IL-1β, IL-18, and pyroptosis modulated by activated caspase-1 play a major role in autoimmune diseases." (PMID 34707607, 2021). "So distinguishing emphasis of different autoimmune disease pathogenesis, which might involve a spectrum from auto-inflammatory to adaptive immune response, may contribute to understand the specific and accurate role of NLRP3 inflammasome." (PMID 34707607, 2021). "Because the NLRP3 inflammasome may trigger the release of IL-1β after stimulation with various danger signals, it represents a potentially effective target to regulate the onset and development of various autoimmune diseases, such as T1DM." (PMID 32973739, 2020). "Previous studies reported associations of PTPN22 and NLRP3 polymorphisms with several autoimmune diseases suggesting their general role in the etiology of autoimmunity, however these risk alleles are not shared among all autoimmune disease." (PMID 30915320, 2019). "NLRP3/caspase-1-dependent IL-1β/IL-18 release or NLRP3/caspase-1-dependent/GSDMD-mediated pyroptosis is crucial in inflammatory disease, autoimmune diseases, tissue injuries and other diseases." (PMID 38957662, 2024). "Pyroptosis is a form of lytic programmed cell death, and it aggravates autoimmune diseases progression via activating NOD-like receptors, especially the NLRP3 inflammasome and its downstream inflammatory factors IL (interleukin)-1β and IL-18." (PMID 37063905, 2023). "Therefore, NLRP3 may be a promising therapeutic target for autoimmune diseases." (PMID 35965334, 2022). "Currently, the role of NLRP3 inflammasome and COX-2 has been documented in many autoimmune diseases." (PMID 34790822, 2021). "Studies have proposed the relationship between IL-1, NLRP3, and COX-2 SNPs and autoimmune diseases such as systemic lupus erythematosus (SLE) and autoimmune thyroid disease." (PMID 34790822, 2021). "The role of the NLRP3 inflammasome in the pathogenesis of several diseases was demonstrated, including CAPS, autoimmune disorders and cancers." (PMID 31118894, 2019). "Anti-inflammatory effects in autoimmune diseases and neurodegeneration also appeared to suppress the inflammatory activity of TLR4-NF-κB/ NLRP3 inflammasome pathway and provided novel mechanistic insights for the potential therapeutic for cervical cancer." (PMID 29423077, 2018).
autoimmune disease (continued). "In autoimmune diseases, HSP70 may regulate excessive immune responses through mechanisms such as inducing regulatory T cell (Treg) differentiation or suppressing NLRP3 inflammasome activation." (PMID 40297581, 2025). "Moreover, we examine the interactive feedback mechanisms among NLRP3 inflammasome, S100A8/A9, and Gasdermin D, exploring their implications in autoimmune diseases." (PMID 40948742, 2025). "Some other NLRP3 inhibitors have been studied for other metabolic and autoimmune diseases, but have not been tested in the context of IIM." (PMID 39723212, 2024). "The distinct functions of ZDHHC12-mediated palmitoylation in regulating the NLRP3 inflammasome and MAVS-mediated antiviral innate immunity may help balance immune responses and prevent autoimmune diseases." (PMID 39621307, 2024). "Some studies postulate that dysfunctional mitochondria (like the ones in autoimmune diseases such as RA and SLE), which release ROS and mitochondrial DNA, may contribute to the activation of the NLRP3 inflammasome." (PMID 38929699, 2024). "Although a large number of mouse studies have shown that NLRP3 inhibitors are effective in the treatment of autoimmune diseases, the clinical use of NLRP3 inhibitors has not been reported." (PMID 35619184, 2022). "It is remarkable that CD38 may facilitate the development of inflammatory and autoimmune diseases by regulating immune response, and CMPK2 is reported to control NLRP3 inflammasome activation." (PMID 35359935, 2022). "Unlike autoimmune diseases such as systemic lupus erythematosus, the renal involvement was rare in NLRP3-AID." (PMID 35668534, 2022). "The accurate role of NLRP3 inflammasome in autoimmune disease pathogenesis is complex and has not yet been completely illuminated." (PMID 34707607, 2021). "Hydroxysafflor yellow A (HSYA) is an effective therapeutic agent for inflammatory diseases and autoimmune disorders; however, its regulatory effect on NLRP3 inflammasome activation in macrophages has not been investigated." (PMID 27433030, 2016). "Clinically, JAK inhibitors (e.g., tofacitinib) already approved for autoimmune diseases show promise in preclinical models by reducing IL-6/STAT3-driven EMT, while TLR4 or NLRP3 inhibitors could blunt the initial DAMP-induced inflammatory cascade that seeds EMT." (PMID 41019090, 2025). "Therefore, along with the NLRP3 inflammasome that forms the cGAS/STING/NLRP3 axis in different inflammatory conditions, NLRs negatively regulating the cGLR (cGAS/STING pathway) system have also evolved to protect the host, including humans, from autoinflammatory and autoimmune diseases." (PMID 38339107, 2024).